ENSG00000288750 (novel transcript)
Gene: Long non-coding RNA gene on chromosome 17 (8,383,648 to 8,384,597, forward strand). Ensembl gene ENSG00000288750.
Gene Ontology:
Biological process: SRP-dependent cotranslational protein targeting to membrane, signal sequence recognition
Cellular component: signal recognition particle, endoplasmic reticulum targeting